CD44 (CD44 molecule (IN blood group))
Diseases named in the same sentence as CD44 in open-access papers (continued):
Sharing a sentence is not in itself a finding about the gene and the disease.
oral cancer (continued). "Given that there is a large amount of CD44 in normal oral tissues, it is difficult to use anti-CD44 antibodies targeting CSCs in oral cancer." (PMID 32576817, 2020). "Nevertheless, we further found that high co-expression of UBE2C and cancer stemness markers, including CD44, D166 and EpCAM, have even worse poor prognosis in TSCC patients, which provided potential diagnostic and prognostic markers in oral cancer patients." (PMID 32899896, 2020). "High co-expression levels of UBE2C/CD44, UBE2C/CD166 and UBE2C/EpCAM were associated with poor prognosis in oral cancer patients from The Cancer Genome Atlas database." (PMID 32899896, 2020). "C44Mab-5 recognized all CD44 isoforms, and showed high sensitivity for flow cytometry and immunohistochemical analysis in oral cancers." (PMID 33000243, 2020). "MOC2-luc is a CD44-expressing syngeneic murine oral cancer cell line that is known to be poorly immunogenic." (PMID 33322807, 2020). "In 2011, a product that qualitatively detected the presence of human CD44 protein (Vigilant Biosciences, Inc., Austin, TX, USA) for aiding in oral cancer diagnosis was announced." (PMID 32823758, 2020). "On the other hand, we previously reported on the antitumor effects of CD44-targeted NIR-PIT in syngeneic murine models of oral cancer using two doses of LED light (50 J/cm2 and 100 J/cm2), which resulted in no complete remission." (PMID 33322807, 2020). "CD44 is also a marker associated with EMT and CSCs in oral cancer and promotes cancer cell aggressiveness by targeting extracellular signal-regulated kinases 1, 2 (ERK1/2)." (PMID 31579438, 2019). "To understand the role of the CD44 low cell population in oral cancer biology, we next analyzed the properties of these cells." (PMID 29515788, 2018). "Ezrin overexpression has been observedin a subpopulation of an oral cancer cell linewhich was CD44+, as a marker of cancer stemcells." (PMID 28670517, 2017). "Real-time polymerase chain reaction (PCR) was used to analyze 6 SNPs of CD44 in 599 patients with oral cancer and 561 cancer-free controls." (PMID 24699672, 2014). "The total percentage of CD44 expression was 57.8%, with 49.3% in oral cancer patients, 66.4% in pharynx and 54.7% in larynx cancer patients expressing CD44." (PMID 24410905, 2014). "Distribution frequency of clinical status and CD44 rs187115 genotype frequencies in 599 patients with oral cancers." (PMID 24699672, 2014). "Although many of these works showed a negative relationship between CD44 protein level and prognosis in oral cancer patients, several reports found that an increased transcriptional level of CD44 indicated disease progression." (PMID 24410905, 2014). "In oral cancer, CD44 expression has been observed to have a significant association with heavy smoking and/or alcohol consumption, thereby predicting poor prognoses." (PMID 24699672, 2014). "Thus, we hypothesized that CD44 polymorphisms play a critical role in oral cancer development." (PMID 24699672, 2014). "Spheres comprised of HNSCC cells or oraspheres and an oral cancer mouse model were used to examine the significance of CD44 cleavage using stable suppression and inhibition approaches." (PMID 24403253, 2013). "Oral cancer CSCs have mostly been isolated using the CD44 marker." (PMID 39941011, 2025). "CD44 expression was predominantly observed on the membrane in oral cancer tissues." (PMID 40291275, 2025). "The CD44 antigen was used as a marker for CSC isolation from oral cancer cell cultures." (PMID 39851519, 2025). "Moreover, it has been found significantly overexpressed in CD44+ cells compared to CD44− cells, suggesting a role in stemness maintenance and regulation of cancer stem cell properties in oral cancer." (PMID 41373532, 2025). "In addition, the expression of ALDH1 and CD44 was a predictor of angiolymphatic invasion and lymph node metastasis in patients with oral carcinomas, respectively." (PMID 37453969, 2023).
oral cancer (continued). "For example, CD44 promotes EMT by upregulating ZEB1 in oral cancer cells." (PMID 36429098, 2022). "Here, aldehyde dehydrogenase 1 (ALDH1) and CD44 were utilized to isolate CSCs of oral cancer." (PMID 35682836, 2022). "In the current study, we aimed to examine whether butylidenephthalide exhibited anti-CSC properties using patient-derived ALDH1+/CD44+ oral cancer cells." (PMID 35682836, 2022). "Another recent study revealed that CD44 overexpression was also associated with advanced T classification, lymphovascular invasion, perineural invasion, poor OS, DSS and recurrence-free survival (RFS) in patients with oral cancer." (PMID 34944493, 2021). "Collectively, these results suggest that treatment with 5-mG2a-f may represent a useful therapy for patients with CD44-expressing oral cancers." (PMID 33000243, 2020). "Among them, CD44 is involved in drug resistance in oral cancer." (PMID 32899896, 2020). "In the present study, we investigated whether anti-CD44 mAbs are advantageous for the treatment of oral cancers." (PMID 33000243, 2020). "Targeting multiple targets, such as EGFR, HER2, PODXL, and CD44 may be needed for effective therapy to conquer oral cancers." (PMID 33000243, 2020). "In this study, we examined whether the developed 5-mG2a-f induced ADCC and CDC in CD44-expressing oral cancer cell lines, such as SAS and HSC-2 cells." (PMID 33000243, 2020). "Moreover, high co-expression of UBE2C/CD44, UBE2C/CD166 and UBE2C/EpCAM was associated with recurrence in oral cancer patients including TSCC patients." (PMID 32899896, 2020). "CD44+/CD36+ cells have been associated with invasion and metastasis in oral carcinoma." (PMID 31847105, 2019). "Among 552 betel-nut chewers, CD44 polymorphisms carriers who smoked had a 4.23–16.11-fold greater risk of having oral cancer compared to those who carried the WT but did not smoke." (PMID 24699672, 2014). "This positive feedback loop supports our hypothesis that an increase in CD44 expression during oral cancer progression could be covered by its shedding." (PMID 24410905, 2014). "Among 731 smokers, CD44 polymorphisms carriers with the betel-nut chewing habit had a 10.30–37.63-fold greater risk of having oral cancer compared to CD44 wild-type (WT) carriers without the betel-nut chewing habit." (PMID 24699672, 2014). "Our data, together with what has been observed in esophageal carcinoma, hypopharyngeal carcinoma, and oral carcinoma, would suggest that the percent of CD44+CD271+ cells might also provide prognostic information." (PMID 25149537, 2014). "Although the functional importance of CD44 SNP rs187115 has not been tested experimentally, an association with the risk of oral cancer is proposed based on the locations of the analyzed variants." (PMID 24699672, 2014). "Distribution frequency of CD44 genotypes in 561 healthy controls and 599 oral cancer patients." (PMID 24699672, 2014). "As CD44 evidently has different roles across the stages of cancer development, it may be upregulated or downregulated by tumor environment cells, providing new information on the involvement of CSCs in the malignant transformation of oral cancer." (PMID 38126564, 2023). "Most researchers have described the intra-cytoplasmatic pattern of the CD44 expression in real, invasive oral cancers, but few have diagnosed its expression in the cytoplasm of the oral epithelium in leukoplakia and explained it considering the interaction of the CD44 antigen with the cytoskeleton." (PMID 34830890, 2021). "CSCs express distinctive cell surface markers that vary across cancer types; for instance, ALDH+, CD44+, and CD133+ in oral cancer; CD34+ in leukemia; and CD200+ and CD166+ in colorectal cancer." (PMID 39200273, 2024). "Among these, HIF1α, CDH1, CD44, EGFR, and CCND1 were identified as the top hub genes that have also been reported as driver candidates responsible for oral cancer initiation and progression." (PMID 37316916, 2023).
oral cancer (continued). "Our study revealed that Cyclin D1, CD44, MAA and SNA-1 offered a sensitivity of 89% and specificity of 92% in delineating HGD and oral cancer." (PMID 37747904, 2023). "This CSCs subpopulation demonstrated higher migration capacity and more resistance to Paclitaxel chemotherapy, in addition to an up-regulation of CD44 and down-regulation of EGFR transcripts in the HN13 oral cancer cell line." (PMID 37065869, 2023). "In the present study, we examined its impact on the cancer stemness traits of oral cancer CSCs in vitro and in vivo, and showed that butylidenephthalide inhibited the expression of Sox2 and Snail in the ALDH1+/CD44+ cells." (PMID 35682836, 2022). "CD44 was also identified as an independent prognostic factor for poor OS, DSS and DFS in patients with advanced oral cancer." (PMID 34944493, 2021). "An additional laboratory ELISA test of this product, also a CE-approved IVD named OncAlert® Oral Cancer LAB Test (Vigilant Biosciences, Florida, USA), provides quantitative values for CD44 and total protein." (PMID 34359370, 2021). "CD44-targeted NIR-PIT combined with IL-15 treatment showed superior in vivo therapeutic efficacy to either CD44-targeted NIR-PIT or IL-15 treatment alone in colon, lung, and oral cancer models." (PMID 32927646, 2020). "Moreover, high coexpression of UBE2C/CD44, UBE2C/CD166 and UBE2C/EpCAM genes was associated with overall survival and recurrence in oral cancer patients including TSCC patients from TCGA database, indicating that UBE2C might be involved in controlling cancer stemness of OSCC." (PMID 32899896, 2020). "Our results based on tests of saliva samples from 131 oral cancer patients and 199 control cases showed that MMP-1 had a sensitivity of 69.5% and specificity of 95.0%, whereas CD44 had a sensitivity of 76.3% and specificity of 57.8%." (PMID 32823758, 2020). "CD44 expression was analyzed in a total of 241 HNSCC cancers, including 86 cancers of the oral cavity, 71 of the oropharynx, and 84 of the larynx." (PMID 31661833, 2019). "In oral carcinoma cell lines and patient samples, CD36+/CD44+ cells were slow-cycling, and, in accordance with transcriptome signatures representing lymph node metastasis, they also homed to lymph nodes in xenografts." (PMID 31661927, 2019). "Aggressive oral cancer cell lines from a murine-oral-cancer model (MOC2, 7, 10) express CD44 and phosphorylated ERK1/2." (PMID 29747682, 2018). "The oncogenic HA-CD44 signal is also involved in chemoresistance, and hyaluronan synthase 2 (HAS2) reportedly induces CD44-dependent CDDP resistance in oral cancer." (PMID 29849953, 2018). "More studies are needed to verify if CD44 is the sole receptor for HA and the involvement of additional SRC-related kinases in HAS3-mediated oncogenic signal axis in oral cancer." (PMID 28107185, 2017). "Although the exact mechanism is unclear, it is possible that even the CD44 expressed in tumors such as breast and oral cancer exhibit the same CSC characteristics, because various detailed mechanisms and signaling pathways are involved in CD44 regulation." (PMID 24699672, 2014). "Moreover, people who were either polymorphic for CD44 in 6 loci (rs1425802, rs187115, rs713330, rs11821102, rs10836347 and rs13347) or who smoked were at a 5.070–9.313-fold risk (p<0.05) of developing oral cancer, compared to people with the WT gene who did not smoke." (PMID 24699672, 2014). "CD44 is a CSC gene and has been observed to be highly expressed in the poorly differentiated metastatic stages of oral cancer patients, leading to invasion, malignancy, and poor prognosis." (PMID 24699672, 2014). "In a study in oral cancer, a connection between ERK1/2 and CD44 was confirmed." (PMID 37047552, 2023). "It has been reported that a combination of CD44- and CD147-positive cells might be more similar to a CSC population than CD133-positive cells in HNSCC and oral cancer." (PMID 36498950, 2022).
oral cancer (continued). "Together, the recognised importance of CD44 as a cancer stem cell marker in oral cancer, and the reversible, non-toxic nature of 1, makes it a promising agent for real time intraoperative imaging." (PMID 34234213, 2021). "For instance, the expression of CD44 predicted survival in patients with pharyngeal and laryngeal tumors, but not in those with oral cancer." (PMID 29212247, 2017). "A similar result was observed for the treatment with A. paniculata in oral cavity cancer cells, significantly inhibiting oncogenicity and promoting radiosensitivity to oral cancer stem cells ALDH1+CD44+ through the upregulation of microRNA-218 and Bmi1 negative." (PMID 38248336, 2024). "According to the analysis above, CD44 indeed participates in oral cancer progression, but cell staining of CD44 may not be accurate enough to reflect the authentic levels of CD44 because of the shedding of CD44." (PMID 24410905, 2014). "Although CD44 was widely expressed in normal oral mucosa, CD44 cleavage was found to occur at a low level or not at all in normal oral mucosa and to be overexpressed in oral cancer tissue, which could be explained by the proteolytic effect of ADAM." (PMID 24410905, 2014). "Furthermore, a lower risk of lymph node metastasis was related with pan-CD44 expression in oral cancer patients (RR = 0.58, 95% CI 0.37 - 0.92), but CD44-v6 expression did not reveal a similar correlation (RR = 0.79, 95% CI 0.29 - 2.12)." (PMID 24410905, 2014). "However, tumor volume reduction of SAS and HSC-2 on day 27 by 5-mG2a-f was still only 43 and 32%, respectively, indicating that anti-CD44 therapy might not be robust enough for conquering most oral cancers." (PMID 33000243, 2020). "In contrast, an anti-CD44 mAb (5-mG2a-f) did not inhibit the growth of SAS or HSC-2 compared to control mouse IgG2a, indicating that 5-mG2a-f did not affect the cell growth of oral cancer cell lines in anchorage-independent condition." (PMID 33000243, 2020).
osteosarcoma (78 papers, 2010 to 2025). A usually aggressive malignant bone-forming mesenchymal neoplasm, predominantly affecting adolescents and young adults. "Research indicates that CRISPR/Cas9 can effectively silence oncogenes, such as CD44, which is implicated in the metastatic behavior of osteosarcoma cells." (PMID 40283955, 2025). "Here, we investigated the role of CD44 in the regulation of drug chemoresistance, using osteosarcoma cells isolated from mice carrying a mutation of the tumor suppressor neurofibromatosis type 2 (Nf2) gene." (PMID 35955749, 2022). "Previous reports correlated expression of cluster of differentiation 44 (CD44) with drug resistance and poor survival of osteosarcoma patients, however the underlying mechanisms are poorly defined." (PMID 35955749, 2022). "In the current study, we applied osteosarcoma tissues and cells isolated from mice with a mutation of the Nf2 gene, to evaluate the function of CD44 in the resistance to chemotherapy." (PMID 35955749, 2022). "There is a low number of detailed studies deciphering the prognostic/diagnostic value of CD44 in sarcomas (excluding osteosarcoma which is one of the most studied and common sarcomas)." (PMID 35785191, 2022). "This meta-analysis was carried out by critically reviewing six studies on the association of CD44 with prognosis in osteosarcoma." (PMID 25112408, 2014). "Most of earlier studies suggested CD44 high expression was associated with high risk of tumor metastasis and worse survival in patients with osteosarcoma." (PMID 25112408, 2014). "However, when it comes to bone sarcomas, the majority of studies have primarily examined CD44, with limited assessment of the CD44v6 variant, primarily in the context of osteosarcoma." (PMID 37491225, 2023). "Moreover, CD44 has been revealed as a useful marker for prognostic and diagnostic (CD44v6 isoform) in osteosarcoma." (PMID 35785191, 2022). "In particular, expression of CD44 was correlated with resistance of human osteosarcoma cells to doxorubicin treatment, but the underlying mechanisms remain unclear." (PMID 35955749, 2022). "Expression of cluster of differentiation 44 (CD44) has been implicated in drug resistance, although the direct mechanism of action in osteosarcoma remains unclear." (PMID 35955749, 2022). "In addition, sarcoma-specific studies involving a greater number of patients are necessary to confirm the influence of CD44 variant expression on the patients’ prognosis (regardless of the utility of CD44v6 as a prognostic marker in osteosarcoma)." (PMID 35785191, 2022). "Nevertheless the Nf2-deficient osteosarcomas express additional CD44 splice variants." (PMID 35955749, 2022). "The interaction partner of CD44, Merlin, was also implicated in osteosarcoma." (PMID 35955749, 2022). "The association between CD44 expression and tumor biology of osteosarcoma is known." (PMID 30093974, 2018). "It is assumed that the enhancement of doxorubicin sensitivity in our study may be induced by loss of function of CD44 when miR-199a-3p concentration is enriched inside osteosarcoma cells." (PMID 26079799, 2015). "Thus, we cannot exclude that splice variants of CD44 might regulate additional processes involved in osteosarcoma chemoresistance." (PMID 35955749, 2022). "Gibbs' research showed that osteosarcoma cells have the ability of forming sarcospheres, and some osteosarcoma cells express mesenchymal stem cell markers, such as Stro-1, CD44, and CD105." (PMID 40083708, 2025). "CD44 was found to increase the resistance of osteosarcoma cells to doxorubicin by upregulating multidrug resistance 1 protein expression." (PMID 38783892, 2024). "For several cell lines including osteosarcoma cells high levels of CD44 correlate with poor prognosis and metastasis and deletion/knockout (KO) of CD44 resulted in reduced tumor cell invasion and proliferation." (PMID 36876041, 2023).